FASTKD2 (FAST kinase domains 2)
Description:
Plays an important role in assembly of the mitochondrial large ribosomal subunit. As a component of a functional protein-RNA module, consisting of RCC1L, NGRN, RPUSD3, RPUSD4, TRUB2, FASTKD2 and 16S mitochondrial ribosomal RNA (16S mt-rRNA), controls 16S mt-rRNA abundance and is required for intra-mitochondrial translation. May play a role in mitochondrial apoptosis.
Synonyms: KIAA0971; COXPD44
Tractability: PROTAC: ubiquitination databases record sites on it; its protein half-life has been measured.
Gene: Protein-coding gene on chromosome 2 (206,765,357 to 206,796,189, forward strand). Ensembl gene ENSG00000118246.
Subcellular location: Mitochondrion matrix, mitochondrion nucleoid; Mitochondrion matrix
Subcellular location (Human Protein Atlas): Mitochondria
Pathways (Reactome):
Metabolism of RNA: FASTK family proteins regulate processing and stability of mitochondrial RNAs; Mitochondrial mRNA modification; rRNA modification in the mitochondrion
Gene Ontology:
Molecular function: protein binding; RNA binding; rRNA binding
Biological process: apoptotic process; mitochondrial large ribosomal subunit assembly; mitochondrial translation; RNA processing; mitochondrial RNA processing; regulation of mitochondrial mRNA stability; mitochondrial RNA modification
Cellular component: mitochondrial matrix; mitochondrial nucleoid; mitochondrion; ribonucleoprotein granule
Genetic constraint (gnomAD): Loss-of-function variants: 29 observed, 32.86 expected, observed/expected ratio (o/e) 0.88, 90% interval 0.66 to 1.2. The upper end of that interval is the gene's LOEUF score, 1.2, which puts it in group 5 of 6, group 1 being the genes least tolerant of losing a copy. Missense variants: 489 observed, 519.9 expected, observed/expected ratio (o/e) 0.94, 90% interval 0.87 to 1.01. Synonymous variants: 186 observed, 195.05 expected, observed/expected ratio (o/e) 0.95, 90% interval 0.85 to 1.08.
Gene-disease validity (ClinGen):
ClinGen rates the evidence that FASTKD2 causes each of these diseases.
mitochondrial disease (autosomal recessive): Definitive.
Homologues: Orthologues: chimpanzee FASTKD2 (99% identical), macaque FASTKD2 (88% identical), pig FASTKD2 (68% identical), dog FASTKD2 (65% identical), mouse Fastkd2 (64% identical), rat Fastkd2 (63% identical), guinea pig FASTKD2 (60% identical), tropical clawed frog fastkd2 (33% identical), zebrafish fastkd2 (28% identical). Paralogues in human: FASTKD1 (15% identical), FASTKD3 (15% identical), TBRG4 (15% identical), FASTKD5 (14% identical), FASTK (10% identical).
Diseases named in the same sentence as FASTKD2 in open-access papers:
FASTKD2 is named in the same sentence as 21 diseases in open-access papers, as found by Europe PMC text mining. Sharing a sentence is not in itself a finding about the gene and the disease. The quoted sentences say what the papers report.
breast carcinoma (4 papers, 2013 to 2021). "IRF-2BP2 is a transcriptional repressor of the proapoptotic gene FASTKD2 (Fas-activated serine-threonine kinase domain 2) in breast cancer cells." (PMID 34356858, 2021). "Knockdown of FASTKD2 by siRNA prevents NRIF3/DD1-mediated apoptosis in breast cancer cells while expression of FASTKD2 leads to apoptosis in all cell types." (PMID 25409762, 2014). "Our findings are consistent with a model where rapid and transient de-repression of the FASTKD2 gene in breast cancer cells leads to apoptosis." (PMID 25409762, 2014). "In our studies, expression of NRIF3/DD1 leads to a rapid 3- to 7-fold increase in FASTKD2 expression within 5–8 h in breast cancer cell lines as well as in LNCaP cells." (PMID 25409762, 2014). "Although FASTKD2 is only derepressed by NRIF3 in breast cancer cell lines, transiently expressed FASTKD2 leads to caspase-2 dependent apoptosis in other cell types (e.g. HeLa cells)." (PMID 23596516, 2013). "Furthermore, ITGB3BP and DIF-1 complexes selectively control cell apoptosis of breast cancer by regulating FASTKD2." (PMID 33974527, 2021). "For breast cancer cells we showed that the DIF-1 complex containing the related proteins IRF-2BP1 and EAP-1 binds to the 5’-untranslated exon of the FASTKD2 gene." (PMID 25409762, 2014). "ChIP analysis indicated that DIF-1, and its related associated proteins IRF2BP1 and EAP-1, bind to the first untranslated exon of the FASTKD2 gene in breast cancer cells while DIF-1 does not bind to the gene in HeLa cells." (PMID 25409762, 2014). "To assess whether FASTKD genes other than FASTKD2 are regulated by NRIF3/DD1, we used qRT-PCR to study expression of all 5 FASTKD genes in both LNCaP-AI cells and T-47D breast cancer cells stably expressing DD1-ERT2." (PMID 25409762, 2014). "DIF-1 acts in a wide variety of breast cancer cells but not other cell types to repress the pro-apoptotic gene, FASTKD2." (PMID 25409762, 2014). "Through microarray and expression studies, we identified FASTKD2 (Fas Activated Serine-Threonine Kinase Domains 2) as the pro-apoptotic target gene that is repressed by DIF-1 in breast cancer cells but not other cell types." (PMID 25409762, 2014). "In microarray studies we previously identified a rapid increase in expression of FASTKD2 in breast cancer cells expressing NRIF3/DD1 but no change in other cells types." (PMID 25409762, 2014). "DIF-1 binds to the FASTKD2 gene in breast cancer cells but not to the FASTKD2 gene in other cell types (e.g. HeLa cells)." (PMID 25409762, 2014). "Thus, like breast cancer cells, DD1-mediated apoptosis of LNCaP cells occurs through expression of the FASTKD2 gene." (PMID 25409762, 2014). "Why NRIF3/DD1 regulates the FASTKD2 gene in breast cancer cells and LNCaP cells but not other cell types is currently unknown." (PMID 25409762, 2014). "However, the DIF-1 complex does not bind to this region of the FASTKD2 gene in HeLa cells which expresses DIF-1, IRF2BP1 and EAP1 at similar levels as in breast cancer cells." (PMID 25409762, 2014).
mitochondrial encephalomyopathy (3 papers, 2016 to 2022). A heterogenous group of disorders characterized by alterations of mitochondrial metabolism that result in muscle and nervous system dysfunction. "Fastkd members are known to present in mitochondria and are dispensable for processing and maturation of certain mt-mRNAs and cellular respiration, and that Fastkd2 gene mutation is linked to mitochondrial encephalomyopathy." (PMID 35754828, 2022). "FASTKD2-mediated post-transcriptional regulation of these genes is a critical cellular process because homozygous nonsense mutations in the FASTKD2 gene are associated with mitochondrial encephalomyopathy." (PMID 27911731, 2016). "Later onset, milder mitochondrial encephalomyopathy, lactic acidosis and stroke-like episode (MELAS)-like syndrome with seizures, stroke-like episodes, and optic atrophy has been described in a Korean family with compound heterozygous mutations in FASTKD2." (PMID 29980628, 2018). "Mitochondrial encephalomyopathy with developmental delay, hemiplegia, convulsions, asymmetrical brain atrophy, and low cytochrome c oxidase (COX) activity in skeletal muscle were reported in patients with mutations in FASTKD2, encoding the fas activated serine-threonine kinase domain 2 protein." (PMID 29980628, 2018).
MELAS (2 papers, 2022 to 2023). "However, variants in FASTKD2 have also been associated with an autosomal-recessive inherited form of MELAS." (PMID 35699875, 2022). "Despite this association, it is unlikely that the heterozygous FASTKD2 variant identified in DGR345 is causative of a MELAS phenotype; however, further study into the effect this variant has on FASTKD2 function may identify a plausible role for this gene and its variants in CSVD." (PMID 35699875, 2022).
pancreatic cancer (2 papers, 2018 to 2021). "Like FASTK, FASTKD2 was upregulated in pancreatic cancer tissues and was associated with poor prognosis." (PMID 34768773, 2021).
prostate carcinoma (2 papers, 2014 to 2021). A carcinoma that arises from epithelial cells of the prostate gland. "The NRIF3/DIF-1/FASTKD2 pathway acts as a “death switch” in breast and prostate cancer cells, how FASTKD2 initiates the apoptotic response will allow for the development of therapeutic agents for the treatment of androgen-independent prostate cancer." (PMID 34150649, 2021). "The NRIF3/DIF-1/FASTKD2 pathway acts as a “death switch” in breast and prostate cancer cells." (PMID 25409762, 2014).
colorectal cancer (1 paper, 2018). A primary or metastatic malignant neoplasm that affects the colon or rectum. "For colorectal cancer, an exhaustive search revealed the FASTKD2, PANK1, and HUWE1 gene triple from the core to have the highest prognostic power (with respect to the training and filtration datasets)." (PMID 29402894, 2018).
developmental delay (1 paper, 2020). "One of these proteins, fas-activated serine-threonine kinase domain 2 (FASTKD2) is tissue specific, and variants in FASTKD2 have been linked to developmental delay and myopathy." (PMID 33426505, 2020).
Leigh syndrome (1 paper, 2023). A progressive neurological disease defined by specific neuropathological features associating brainstem and basal ganglia lesions. "Our findings revealed two novel variants in the NDUFAF5 and FASTKD2 genes, which were associated with the development of Leigh syndrome and Leigh-like syndrome, respectively." (PMID 38283147, 2023).
lung adenocarcinoma (1 paper, 2024). A carcinoma that arises from the lung and is characterized by the presence of malignant glandular epithelial cells. "It is the first time to confirm that FASTKD2 is an independent prognostic indicator of lung adenocarcinoma." (PMID 38495508, 2024). "It is confirmed that the expression value of FASTKD2 is a predictor of prognosis of lung adenocarcinoma." (PMID 38495508, 2024). "In order to further prove the relationship between FASTKD2 gene and mitochondrial dynamics related genes, the TCGA database was used to download the gene sequencing data of 59 paracancerous samples and 535 lung adenocarcinoma patients' cancer samples." (PMID 38495508, 2024). "In order to further explore the role of FASTKD2, we evaluated the value of high expression of FASTKD2 as a predictor of lung adenocarcinoma for the first time, with a sensitivity of 0.949, which is particularly conducive to the screening of lung adenocarcinoma." (PMID 38495508, 2024).
metastatic cancer (1 paper, 2014). A carcinoma which has spread from the original site of growth to another anatomic site. "The NRIF3/DD1/DIF-1/FASTKD2 pathway is a new pathway to therapeutically target Estrogen Receptor negative breast or androgen independent prostate cancer or metastatic cancer for therapy." (PMID 25409762, 2014).
pancreatic ductal adenocarcinoma (1 paper, 2021). An infiltrating adenocarcinoma that arises from the epithelial cells of the pancreas. "A study found an association between dysregulated FASTKD2 and poor prognosis of patients with pancreatic ductal adenocarcinoma, through FASTKD2’s role in promoting tumor growth and invasion, via upregulation of c-Myc expression." (PMID 33917098, 2021).
cancer (6 papers, 2010 to 2024). A tumor composed of atypical neoplastic, often pleomorphic cells that invade other tissues. "Five hypermethylated regions were in genes previously associated with cancer (TRAP1, SLC38A3, CHRM1, EDN2, and PROX1), while six hypomethylated regions were in genes previously associated with cancer (NUMBL, ALDH1B1, FTCD, FASTKD2, FAM96A, and ARHGAP15)." (PMID 36474183, 2022). "First, two studies by the same research group show that FASTKD2 is highly proapoptotic in various cancer cell lines and demonstrate that its expression is tightly controlled by the transcriptional complex NRIF3-DIF-1 in breast and prostate cancer cell lines." (PMID 34768773, 2021). "Therefore, we have further explored the possible mechanism of DHEA in preventing and inhibiting cancer through mitochondrial pathway, and creatively explored a new target, FASTKD2." (PMID 38495508, 2024). "Comparing HCC in the choline deficient model and choline supplemented model, significant methylation differences were seen in 11 genes previously associated with cancer (hypermethylation of TRAP1, SLC38A3, CHRM1, EDN2, and PROX1; hypomethylation of ALDH1B1, FTCD, FASTKD2, FAM96A, and ARHGAP15)." (PMID 36474183, 2022). "Finally, we highlight a few in vitro studies that provide mechanistic links between FASTK, FASTKD2 and cancer." (PMID 34768773, 2021). "These interesting results not only reveal the known relationship of FASTK proteins to mitochondrial physiology, but also uncover the particular interaction of FASTK, FASTKD2, FASTKD4 and FASTKD5 with cancer signaling pathways." (PMID 34768773, 2021). "As reviewed in the introduction, several studies have previously reported upregulation of FASTK, FASTKD1, FASTKD2 and FASTKD3 in certain types of cancer." (PMID 34768773, 2021). "Among these proteins, we have identified many differentially abundant proteins identified as having a role in cancer (IFIT1, FASTKD2, PIP4K2B, ARID1B, SLC25A33: overexpressed in TR; CALD1, CPA3, B3GALT5, CD177, RIPK1: overexpressed in NR)." (PMID 29681787, 2018). "Finally, the protein-protein interaction network for FASTK proteins uncovers the interaction of FASTK, FASTKD2, FASTKD4 and FASTKD5 with cancer signaling pathways." (PMID 34768773, 2021). "Finally, we provide novel evidence of the PPI network of FASTK proteins, which uncovers the interaction of FASTK, FASTKD2, FASTKD4 and FASTKD5 with cancer signaling pathways." (PMID 34768773, 2021). "We have identified many differentially abundant proteins already identified as having a role in cancer, such as the earlier discussed proteins IFIT1, FASTKD2, PIP4K2B, ARID1B and SLC25A33 (more abundant in TR) or CALD1, CPA3, B3GALT5, CD177 and RIPK1 (more abundant in NR)." (PMID 29681787, 2018).
tumor (5 papers, 2019 to 2026). "Structure-function screening revealed antibiotic linezolid inhibited FASTKD2 interactions with mitochondrial RNA, thereby disrupting tumour network communication and augmenting efficacy of therapies targeting neuronal stimulation of tumour cells." (PMID 41994142, 2026). "Targeting FASTKD2 attenuates tumour stemness and growth, disrupting coordinated mitochondrial RNA metabolism in TMs, which sustains intercellular communication and tumour proliferation." (PMID 41994142, 2026). "The results showed that DHEA could down regulate the expression of FASTKD2 in tumor of mice." (PMID 38495508, 2024). "Furthermore, some of these proteins act as tumour suppressors, by proapoptotic and increasing cell survival (e.g., FASTKD3) while othersact as pro-oncogenes and poor prognostic factors (FASTK, FASTKD2, FASTKD4)." (PMID 36518140, 2022).
FASTKD2 also shares sentences with these, for which no sentence is quoted: bone metastasis (1 paper); gastric cancer (1); heart failure (1); lactic acidosis (1); lung carcinoma (1); myopathy (1); new-onset refractory status epilepticus (1); Stroke (1).